MMP7 (matrix metallopeptidase 7)
Diseases named in the same sentence as MMP7 in open-access papers (continued):
Sharing a sentence is not in itself a finding about the gene and the disease.
liver cancer (11 papers, 2013 to 2024). An epithelial or non-epithelial malignant neoplasm that arises from the liver. "Isofraxidin can effectively inhibit the growth of MMP-7 and cancer cells in patients with liver cancer and reduce the invasive ability of cancer cells." (PMID 39830344, 2024). "Their insights into the mechanism revealed FOXM1’s role in promoting liver cancer cell invasion and metastasis by upregulating MMP-7, RhoC, and ROCK1, with HBx further amplifying FOXM1 expression through the ERK/CREB pathway." (PMID 37817774, 2023). "YEATS2 acts through the PI3K/AKT/MMP7 signaling pathway and affects the progression of liver cancer." (PMID 36980736, 2023). "Our subsequent recovery experiments found that the PI3K inhibitor LY294002 reversed the promotion effect of YEATS2 on the migration and invasion of liver cancer cells and the expression of MMP7." (PMID 36980736, 2023). "Consistently, we also observed an increased expression of the Bcl-2, c-Myc, cyclinD1, and MMP7 target genes in primary liver cancer tissue from DEN-treated mice (red columns); however, the DEN-stimulated expression of these genes was significantly restrained by the absence of Gab2 (green columns)." (PMID 28842424, 2017). "Thus, GXI might inhibit metastasis of liver cancer via MMP-7 and MMP-9 inhibition." (PMID 31569691, 2019). "Rd has been shown to inhibit migration of liver cancer cell lines HepG2 by reducing expression of MMP-1, MMP-2 and MMP-7." (PMID 24130681, 2013). "In addition to the EMT regulated by Snail, nuclear Snail was also reported to play an another key role in regulating cell invasion by inducing increases in MMPs, such as MMP-1, MMP-2, MMP-7, MMP-9, and MMP-14, in ovarian, oral, and liver cancers." (PMID 36766694, 2023).
gastric adenocarcinoma (10 papers, 2010 to 2025). "MMP-7 belongs to the matrix metalloproteinase family and plays a critical role in the invasion and growth of gastric adenocarcinoma by degrading various protein components of the extracellular matrix." (PMID 40689396, 2025). "Expression of MMP-7 has been found to correlate with invasive property and advanced tumor stage of head and neck squamous cell carcinoma, and endometrial and gastric adenocarcinoma." (PMID 22863036, 2012). "The aim of this study was to investigate whether the expression of MMP2, MMP7, and MMP9 in humans is associated with the expression of mTOR in its “naïve” and its phosphorylated (active) form in different topographical regions of gastric adenocarcinomas." (PMID 26652716, 2015). "Activation of MMP-7 by DKK1 and Wnt/β-catenin pathway is known to induce T-DM1 or ado-trastuzumab resistance, and lead to poor prognosis in gastric adenocarcinoma." (PMID 33918254, 2021). "In the same way, in gastric adenocarcinoma cell lines, ETV4 increases MMP1 and MMP7 expression and stimulates invasion in vitro." (PMID 29996935, 2018).
periodontitis (10 papers, 2015 to 2025). An acute or chronic inflammatory process that affects the tissues that surround and support the teeth. "CSF3, ICAM2, and MMP7 serve as diagnostic and prognostic biomarkers for periodontitis." (PMID 36457739, 2022). "Enhanced transcriptional and inductive IL-1β and MMP-7 expressions in periodontitis-affected gingiva can eventually potentiate and complement the Td-dentilisin-mediated microbial-dependent activation of the degranulated latent proMMP-8 to aMMP-8." (PMID 38786309, 2024). "Specifically, MMP7 was considered a new target in predicting poor wound healing in apical periodontitis and, most recently, as novel salivary biomarkers for periodontitis." (PMID 35631379, 2022). "The concentrations of MMP-3 and MMP-7 are markedly increased in the GCF of patients with periodontitis." (PMID 32650590, 2020). "The top two most up-regulated genes were MUC4 and MMP7, and the corresponding proteins of these genes were also overexpressed in gingival tissue from patients with periodontitis." (PMID 26686060, 2015). "Our novel findings suggest MUC4 and MMP7 to be potential biomarkers and therapeutic targets for periodontitis." (PMID 26686060, 2015). "The present RNA-seq study of the global transcriptome of periodontitis identified MUC4 and MMP7 as the two most highly up-regulated genes in periodontitis." (PMID 26686060, 2015). "In the current study, MMP7 was identified as the second most highly up-regulated gene in periodontitis." (PMID 26686060, 2015). "Notably, the expression of CypA and MMP-7 was more prominent in areas with dense inflammatory infiltrates, which were primarily present in periodontitis cases." (PMID 40075856, 2025). "In addition, serum or plasma levels of MMP-7 are elevated in Helicobacter pylori infection and periodontitis." (PMID 33005257, 2020). "Thus, our current findings indicate that MMP7 may play a crucial role in the pathogenesis of periodontitis." (PMID 26686060, 2015). "Immunohistochemical analysis revealed significant differences in the immunopositivity for MMP-7, EMMPRIN, and CypA, with the highest expression levels observed in chronic periodontitis samples, followed by chronic gingivitis and healthy gingiva samples." (PMID 40075856, 2025). "On the other hand, it is known that the MMP-8′s up-regulator’s IL-1β mRNA and activator MMP-7 mRNA and potential endogenous inhibitor TIMP-1 mRNA can be de novo transcriptionally up-regulated in the diseased periodontitis gingivae." (PMID 38786309, 2024). "Thus, decreased expression of Mmp7 induced by (3S)-vestitol treatment could be considered another relevant finding that justifies future studies testing the effects of (3S)-vestitol on inflammatory diseases such as periodontitis." (PMID 35631379, 2022). "There seems to be a significant increase in MMP expression and activity in chronic periodontitis, especially MMP-1, MMP-3, MMP-7, MMP-8, and MMP-9, with minor contributions from MMP-13 and MMP-14." (PMID 32650590, 2020). "The two most up-regulated genes in connection with periodontitis, MUC4 and MMP7, were investigated further." (PMID 26686060, 2015). "In this study, we aimed to (i) detect Td-dentilisin and MMP-8 immunoexpression levels in gingival tissue samples of patients with periodontitis compared with periodontally healthy gingivae to (ii) assess the MMP-8, MMP-2, MMP-7, TIMP-1, and IL-1β mRNA expressions in the diseased vs. healthy gingiva." (PMID 38786309, 2024). "Our study is the first to link MMP7 to periodontitis, showing it to be overexpressed at the protein level in gingival connective tissue, but not in the gingival epithelium of patients with periodontitis." (PMID 26686060, 2015).
esophageal cancer (9 papers, 2015 to 2024). A primary or metastatic malignant neoplasm involving the esophagus. "At last, 12 associations (MMP-2 rs243865 with esophageal cancer and LC, MMP-7 rs11568818 with bladder and CC, and MMP-9 rs3918242 with BC) were rated as strong evidence for cancer risk, 7 as moderate evidence, and 15 as weak." (PMID 35574300, 2022). "Finally, 12 associations (MMP-2 rs243865 with esophageal cancer risk and LC risk, MMP-7 rs11568818 with bladder risk and CC risk, and MMP-9 rs3918242 with BC risk) were rated as strong evidence, 7 as moderate evidence, and 15 as weak." (PMID 35574300, 2022). "In particular, the authors found that increased MMP-7 expression in esophageal cancer patients was positively correlated to TNM stage III-IV (odds ratio (OR) 3.04, 95% confidence interval (CI) 1.43–6.46, p = 0.004)." (PMID 33672007, 2021). "We further found that depletion of V-ATPase V1E1 led to reduced expression of vimentin, MMP2, and MMP7, which are critical for metastasis of esophageal cancer cells." (PMID 27384996, 2016). "MMP-7 is a metalloproteinase over-expressed in cancers with high propensity to invasion and metastasis, and high serum levels of anti-MMP-7 are found in esophageal cancer patients and are connected to staging and invasiveness." (PMID 33672007, 2021).
pancreatic ductal adenocarcinoma (9 papers, 2017 to 2024). An infiltrating adenocarcinoma that arises from the epithelial cells of the pancreas. "Evaluating the level of MMP7 expression in fine‐needle aspiration biopsy samples after diagnosis can help identify individuals with surgically removed pancreatic ductal adenocarcinoma who would benefit the most from neoadjuvant therapy." (PMID 39187937, 2024). "MMP7 is overexpressed in pancreatic intraepithelial neoplasia (PanINs) and pancreatic ductal adenocarcinoma (PDA) and has been found to promote the initiation and progression of PDA; it is also correlated with the reduced survival and distant metastasis of PDA." (PMID 35741777, 2022). "A previous study has also reported that a high serum MMP7 expression level is considered a useful clinical candidate to predict tumor stage and survival in patients suffering from pancreatic ductal adenocarcinoma and other types of cancers, including colon, ovarian and digestive system cancers." (PMID 35659367, 2022). "Circ-0007334 regulates MMP-7 and collagen type I alpha 1 chain (COL1A1) by competitively adsorbing miR-144-3p and miR-577 to enhance the expression and functions of MMP-7 and COL1A1 in pancreatic ductal adenocarcinoma (PDAC)." (PMID 31973726, 2020).
esophageal squamous cell carcinoma (8 papers, 2013 to 2022). Esophageal squamous cell carcinoma (ESCC) is a type of esophageal carcinoma (EC) that can affect any part of the esophagus, but is usually located in the upper or middle third. "In esophageal squamous cell carcinoma, Activin A has been associated with tumor aggressiveness and increased MMP-7 expression." (PMID 26447543, 2015). "It is shown that the polymorphism in MMP7 promoter increases susceptibility to esophageal SCC." (PMID 26297502, 2015). "In esophageal squamous cell carcinoma (ESCC), overexpression of ATF4, a PERK effector, is involved with increased expression of MMP-2 and MMP-7 to promote invasion and metastasis of ESCC in vitro and in vivo." (PMID 33746610, 2021). "Finally, increased expression of ATF4 in esophageal squamous cell carcinoma correlates with invasion and metastasis, an effect attributed to increased transcription of MMP-2 and MMP-7." (PMID 27802179, 2016).
Hypertension (8 papers, 2014 to 2025). The presence of chronic increased pressure in the systemic arterial system. "It has been shown that MMP-7 and ADAM-12 are functionally connected in agonist-induced transcriptional events that may ultimately result in the development of hypertension and cardiovascular hypertrophy." (PMID 26571308, 2015). "However, when evaluated together in multivariable analysis with other predictors (age, hypertension, ischemia on MRI) imbalanced between survivors and non-survivors, MMP-7 was together with age, the only significant predictors of mortality, with the strongest association with MMP-7." (PMID 24400123, 2014).
lung diseases (8 papers, 2013 to 2024). "The diagnostic potential of MMP-7 was analyzed in terms of its ability to discriminate between the different lung diseases." (PMID 24336111, 2013). "Serum MMP-7 levels seem to be capable of distinguishing IPF patients from those with any other lung disease." (PMID 24336111, 2013). "In the present study we compared MMP-7 and fcDNA levels in patients with different pulmonary diseases, including IPF, other IIPs including iNSIP and chronic HP and NSCLC, with those of healthy individuals." (PMID 24336111, 2013). "We also analyzed the diagnostic potential of MMP-7 in terms of its sensitivity and specificity in discriminating between NSCLC patients and healthy donors or individuals with other lung disease together with other IIPs including NSIP and chronic HP patients." (PMID 24336111, 2013). "MMP-7 is a profibrotic factor that contributes to the pathogenesis of various lung diseases." (PMID 30911386, 2019). "We compared the activities of MMP‐7 in blood and MMP‐2 and ‐9 in BALF of CIPF dogs, dogs with other lung diseases, and healthy dogs." (PMID 33274549, 2021). "MMP-7 was higher in TSC-LAM patient, with even greater values in patients with TSC-LAM minor pulmonary disease, than in S-LAM patients, and in controls (p = 0.001)." (PMID 33981713, 2021). "The combination of MMP-7 and fcDNA was evaluated for its potential to discriminate between NSCLC patients and those with other lung diseases and healthy donors." (PMID 24336111, 2013). "Although our findings concur with several studies in humans, no previous reports of blood MMP‐7 in any lung diseases of dogs exist to our knowledge." (PMID 33274549, 2021). "The aim of the study was to explore the role of MMP-2 and MMP-7, such as vascular endothelial growth factor (VEGF) -C and -D in women with LAM, including patients with minor pulmonary disease (i.e., <10 lung cysts), and TSC with or without LAM." (PMID 33981713, 2021). "It has been shown that serum MMP-7 levels are significantly elevated in patients with IPF compared with healthy controls and lung diseases other than ILDs and non-IPF ILDs." (PMID 34501312, 2021). "It has also been shown that serum MMP-7 levels are higher in IPF patients, including asymptomatic ones, than in individuals with other non-malignant lung diseases, indicating its potential usefulness as a marker for the early non-invasive diagnosis of IPF." (PMID 24336111, 2013).
ovarian tumor (8 papers, 2015 to 2025). "For example, MMP7 encodes matrix metalloproteinase-7 and facilitates the invasion and migration of ovarian tumor cells by remodeling the extracellular matrix." (PMID 36907877, 2023). "Condition-specific analysis of MMP7 showed highest values in ovarian tumor study, colorectal adenoma study, and transwell differentiation study." (PMID 38803919, 2024). "We observed higher SE ranges of MMP-7 and tumor markers in more advanced ovarian tumor stages (exception – TIMP-1)." (PMID 28662671, 2017). "In summary, to the authors’ knowledge, our report is the first to evaluate the diagnostic usefulness of MMP-7 and TIMP-1 independently and, especially, in combination with both established ovarian tumor markers." (PMID 28662671, 2017). "MMP7 was observed to be an independent prognostic factor, with higher MMP7 expression in ovarian tumor cells correlating with good clinical and survival parameters." (PMID 26579497, 2015). "MMP7 promotes invasion and migration of tumor cells via extracellular cleavage of E-cadherin, and also can activate other MMPs, such as proMMP2 and proMMP9, to facilitate ovarian tumor invasion." (PMID 27835587, 2016).
acute kidney injury (7 papers, 2016 to 2025). Sudden and sustained deterioration of the kidney function characterized by decreased glomerular filtration rate, increased serum creatinine or oliguria. "Finally, liver specificity is a potential issue with serum biomarkers in general; HA, for example, can be affected by liver or renal failure, and MMP7 is associated with cancers and other fibrotic conditions." (PMID 27861569, 2016). "We urge more research with longer study timeframes and bigger samples to figure out the long-term impact of urine MMP-7 in forecasting renal failure." (PMID 40026998, 2025). "The function of MMP-7 in renal disorders is multifaceted: it can exhibit protective function in acute kidney injury by degrading E-cadherin and Fas-Ligand (a TNF family protein)." (PMID 37626956, 2023). "Both lithium and MMP-7 have initial protective effects for acute kidney injury, supposedly by priming tubular epithelial cells for survival and regeneration." (PMID 35136035, 2022). "Acute kidney injury was associated, and to a certain degree, predicted by IFNg, TWEAK, MMP7, and MUC-16." (PMID 34608231, 2021).